CD4 (CD4 molecule)
Diseases named in the same sentence as CD4 in open-access papers (continued):
Sharing a sentence is not in itself a finding about the gene and the disease.
cancer (continued). "PER1 expression in OV was positively correlated with neutrophils, regulatory T cells (Tregs), M2 macrophages, cancer-associated fibroblasts, naïve B cells, activated dendritic cells, and resting CD4+ memory T cells, and negatively correlated with B cells and M1 macrophages." (PMID 34220965, 2021). "CD4 lymphocyte nadir had a complex association with cancer in this cohort." (PMID 33803641, 2021). "The analysis results showed that the FSTL3 expression was more positively associated with abundances of TIICs such as cancer-associated fibroblasts (CAFs), macrophages (M1- and M2-like), myeloid dendritic cell and CD4+/CD8+ cells, whereas it was negatively associated with B cells and NK cells." (PMID 34335633, 2021). "However, for the severe CD4 nadir category, the risk of cancer persisted at 5 years (RR = 2.33, 95% CI [1.27, 4.11], p = 0.0042) and at 10 years (RR = 1.77, 95% CI [1.04, 3.02], p = 0.0305)." (PMID 33803641, 2021). "Low CD4+ cell count is associated with increased cancer risk, especially NADC." (PMID 34941669, 2021). "Impaired immunity could be certainly playing a role, as CD4 count depletion is associated with malignancy." (PMID 33882093, 2021). "The results indicated that ANXA4 expression was significantly associated with B cell in 15 cancer types, macrophage in 17 cancer types, dendritic cell in 20 cancer types, neutrophil in 16 cancer types, CD4+ T cell in 14 cancer types, and CD8+ T cell in 16 cancer types." (PMID 34540918, 2021). "Subsequently, in each cancer type, the gene expression of selected immunomodulatory genes, frequencies of nonsynonymous mutations, and levels of T CD4 and T CD8 were compared between subtypes and normal adjacent tissues by means of multivariate, nonparametric ANOVA-type statistics." (PMID 33282963, 2020). "Additionally, we divided patients into a low HNF1B expression group and a high HNF1B expression group, and CD8+ T cell, CD4+ T cell and B-cell levels were distinctly associated with overall survival of cancer patients in the different groups." (PMID 33173410, 2020). "In addition, YTHDF2 expression was associated with CD8+ T cell levels in 12 cancer types, CD4+T cell levels in 14 cancer types, macrophage levels in 14 cancer types, neutrophil levels in 12 cancer types, and DC levels in 12 cancer types." (PMID 32986017, 2020). "CD4+ T-cell suppression or dysfunction has been reported as the mechanism causing cancer escape." (PMID 32552719, 2020). "In a predictive point of view and based on determined cut-offs, high frequency of CD8+CD45RChigh and low frequency of CD4+CD45RChigh T cells allowed to predict a >20-fold and a nearly 4-fold increased risk of developing AR and cancer, respectively, after adjustment on classical risk factors." (PMID 30925186, 2019). "After a mean follow-up of 11.1±4.1 years, cancer occurred in 25 patients (28.1%) and was associated with a decreased pre-transplant proportion of CD4+CD45RChigh T cells, with a frequency below 51.9% conferring a 3.7-fold increased risk of post-transplant malignancy (HR 3.71 [1.24–11.1], p = 0.019)." (PMID 30925186, 2019). "Next, we intended to ascertain whether the CD4+ TCR Vβ9 TIL clone obtained was able to recognise any of the mutated peptides tested earlier in the screening assay to gauge for anti-cancer peptide-specific reactivity." (PMID 30377343, 2019). "Given the in vitro cytokine profile of CD4+CD45RClow T cells, this observation suggests that an unbalanced Th1/Th2 ratio in favor to a Th2 response may predispose to cancer development in kidney transplant recipients." (PMID 30925186, 2019). "Furthermore, our studies suggest that past or current HBV infection coupled with low CD4 count or nadir or low CD4:CD8 ratio is a profile associated with increased risk of developing virus-associated cancers in otherwise healthy HIV-seronegative men." (PMID 30315476, 2018).
cancer (continued). "Our data suggest these prognostic markers have predictive value for risk of virus-associated cancers over a 6- to 8-year window prior to diagnosis; a subset of cases had chronically low CD4 and/or low CD8 counts as long as 10 years or longer prior to diagnosis." (PMID 30315476, 2018). "Additionally, CD4 count at cancer diagnosis has been less consistently associated with survival in patients with NADC." (PMID 29760767, 2018). "Low CD4+ cell counts predisposes them to develop cancers hence the need for a close surveillance." (PMID 30607173, 2018). "Next, we sought to determine if additional immunological parameters that could influence virus-associated cancer risk were detected among subjects with low CD4 nadir." (PMID 30315476, 2018). "Furthermore, multivariate analysis showed that higher numbers of CD4+ TILs in the invasive front of cancer stroma were significantly associated with higher survival rate." (PMID 29732001, 2018). "Current CD4 cell count-nadir differential was a better predictor of incident virus-associated cancers (adjusted HRs/100 cells/μl decrease and 95% CI 1.27 [1.09, 1.48], p = 0.002) than recent CD4 count (adjusted HRs/100 cells/μl decrease [95% CI] 1.17 [1.03–1.33]; p = 0.014)." (PMID 30315476, 2018). "Also, the methylation of TRIM27, a negative regulator of CD4 T cells also involved in the development of cancer, was identified to be associated with change in lung function over the 11-year period." (PMID 29299071, 2017). "We designed MAG-Tn3, a fully synthetic vaccine based on three consecutive Tn moieties that are O-linked to a CD4+ T cell epitope, to induce anti-Tn antibody responses that could be helpful for therapeutic vaccination against cancer." (PMID 26847142, 2016). "Additionally, we showed that SOX2-OT inverted the transcriptional association of STAT4 to CD4, which plays a key role in cancers." (PMID 26943771, 2016). "Le taux de CD4 ne semble pas avoir d'influence sur la survenue ou le stade du cancer du sein car le taux de CD4 était supérieur à 350 élts/ml dans 4 fois sur 6 au moment du diagnostic du cancer du sein." (PMID 26523196, 2015). "Foxp3+CD4+ T cells may benefit the host by modulating inflammation, which is linked to the angiogenesis of cancer." (PMID 26604855, 2015). "Low CD4 lymphocyte counts may predict cancer risk, while other studies have focused on immune-regulatory or effector cell populations." (PMID 25250867, 2014). "Importantly, cancer incidence in HIV-infected individuals was found to be inversely related to CD4+ T cell counts in blood, which supports the association between immunosuppression and increased cancer risk." (PMID 24860567, 2014). "This may be important to the design of vaccines for cancer patients who are deficiency of CD4+ Th and/or display profound immune suppression." (PMID 25941586, 2014). "Our previous work and that of many others revealed that CD4+ cells are a basic cellular carrier of microbially-triggered signals that shape the immune system to restore homeostasis in inflammatory-associated pathologies, cancer, and reproductive health." (PMID 24205344, 2013). "However, one of the major obstacles in this therapy is the poor survival of transferred TILs or CTL clones, and the development of corrupted CTL memories due to AICD and the CD4+ T cell-deficient environment, typically associated with primary cancer therapies." (PMID 23785406, 2013). "Although loss of CD4 expression on lymphocytes is known to correlate with the cytotoxic function, the role of CD4 expression in cancer cells remains unclear." (PMID 12402156, 2002). "Numerous studies have shown that mast cells, CD4+ memory T cells, M0 macrophages, and quiescent natural killer (NK) cells are associated with cancer recurrence and progression, whereas dendritic cells, CD8+ T cells, and M1 macrophages may be effector cells for anticancer treatment." (PMID 40458559, 2025).
cancer (continued). "Numerous studies have identified cytotoxic CD8+T lymphocytes (CTL), CD4+T helper cells 1 (Th1 cells), and natural killer cells (NK) as primarily exerting anti-cancer effects, while CD4+Th2 cells and myeloid-derived suppressor cells (MDSCs) are associated with pro-cancer effects." (PMID 41210692, 2025). "CIBERSORT analysis showed that SLC2A3 expression was positively associated with CD4 memory-activated T cells, M0 macrophages, activated mast cells, and neutrophils, but negatively correlated with regulatory T cells (Tregs), activated NK cells, and memory B cells in most cancers." (PMID 41268544, 2025). "The decrease in the CD4+ T cell ratio in patients with biliary obstruction compared with patients with non-obstructive disease may cause a decrease in OS because it may cause cancer progression." (PMID 38710890, 2024). "However, many studies have revealed that a high abundance of CD4 + Th1 cells is associated with poorer prognosis in various cancers, including PDAC, consistent with our findings indicating that hypomethylation of the PD-L1 promoter correlates positively with worse survival outcomes." (PMID 38833018, 2024). "Finally, the expression of CD4 in particular may be helpful to identify early-stage OSCC patients with high or low risk of cancer recurrence and/or progression." (PMID 38926643, 2024). "Immune dysregulation was an independent risk factor for cancer (OR 2.19, p=0.04), alongside previous immunosuppressant therapy (OR 2, p=0.031), higher IgM levels (OR 1.008 per SD, p=0.012), older age (OR 1.04, p<0.001), and lower CD4 cell counts at diagnosis (OR 0.997, p<0.001)." (PMID 39478863, 2024). "Furthermore, TMED1 expression was positively associated with the infiltration levels of regulatory T cells (Tregs), cancer-associated fibroblasts (CAFs), and endothelial cells and negatively correlated with the infiltration levels of CD4+ T cells, CD8+ T cells, and B cells." (PMID 38392302, 2024). "As such, not only were these particular cell types unevaluable in the cancer-associated admixtures, but a population that was present, such as memory CD4+ T cells, may have been easier to distinguish within them because closely related naïve CD4+ T cells were not included." (PMID 39191725, 2024). "Moreover, the expression of the YAP1 pathway gene signature was significantly and positively associated with the infiltrating levels of immunosuppressive stromal cells, including cancer-associated fibroblasts, macrophage and Tregs, but negatively associated with antitumoral CD4 Th1." (PMID 37173920, 2023). "However, memory and Th2 CD4+ T cells, mast cells, and common lymphoid progenitor were most positively associated with the DHX9 in these different cancers, while effector memory CD4+ T cells and NK T cells, macrophages, and monocytes were negatively associated with the expression of DHX9." (PMID 37214432, 2023). "Furthermore, it has been reported in mice that CD4 T cells may indirectly kill cancer cells via tissue remodeling and hypoxia-associated mechanisms." (PMID 37185301, 2023). "Interestingly, It has been described that MDSCs may cause Tregs expansion, mainly in the context of cancer, but there are reports describing that MDSCs are also able to suppress CD4+ Foxp3+ differentiation from CD4 naïve T cells via ROS and the IDO enzyme." (PMID 36250061, 2022). "Interestingly, the survival curves showed that low expression of GPX7 along with low immune infiltration of CD4+ T cells, neutrophil, myeloid dendritic cell (mDCS) and cancer associated fibroblast (CAF) have better prognosis than the high TIL- and GPX7-expressing group in LGG." (PMID 35440701, 2022). "In addition, some non-synonymous cancer mutations were immunogenic, and most immunogenic mutations could be recognized by CD4+ T lymphocytes." (PMID 36700197, 2022).
cancer (continued). "The results showed that the CD209 expression was evidently correlated with the infiltration of CD8+ T cells, CD4+ T cells, Treg cells, B cells, monocytes, NK cells, myeloid dendritic cells, neutrophils, macrophages, and cancer-associated fibroblasts in pan-carcinoma patients." (PMID 35783255, 2022). "Therefore, it is not clear whether the observed increase in the relative peripheral CD4+ percentage is the result of a direct effect on the immune system or a reduction in the damage to the immune system caused by the cancer therapy." (PMID 34836336, 2021). "To summarize, we assume that the observed reduction in the number of IFN-gamma-producing CD4+ T cells might be simultaneously associated with an increased release of IFN-gamma into the cancer cell micro-environment in triple-negative MDA-MB-231 cancer cells." (PMID 34440813, 2021). "However, temporal analysis of the risk of cancer by CD4 nadir revealed a 3.53-fold and 6.19-fold relative risk of cancer at 1 year for advanced and severe CD4 nadir, respectively, compared to normal CD4 nadir." (PMID 33803641, 2021). "Initially, the reduction in AIDS-associated cancers was attributed to the immune reconstitution of the body as a result of improved CD4+ T cell count and the reduction in overall viral load; however, later reports suggested that direct off-target anti-cancer action by HIV-PIs could be possible." (PMID 33228205, 2020). "Importantly, myeloid cells and CD4 T cells expressed markers associated with a dysfunctional phenotype even in the preinvasive stage, suggesting that the suppressive environment precedes the development of cancer." (PMID 32908137, 2020). "Moreover, we were able to confirm our hypothesis by showing in our population that a low proportion of CD4+CD45RChigh T cells was associated with cancer occurrence." (PMID 30925186, 2019). "In the present manuscript, we could indeed transfer the activity of PTM to CD4+ T cells boosting T cell proliferation and cytokine production in the presence of cancer cells, which further underlines underpinning previous data using a CTLA-4-CD28 fusion receptor." (PMID 30214445, 2018). "In another study, allergen-induced pulmonary inflammation was linked to a higher risk of lung experimental metastasis due to a CD4+ T cell-mediated activation of the vascular endothelium, which, in microfluidic in vitro assays, was required for an enhanced transendothelial migration of cancer cells." (PMID 30200242, 2018). "Moreover, there is considerable heterogeneity across NADM, and over time, and it can be difficult to infer direct clinical benefits of HAART uptake from epidemiological trends, although we suggest that overall we see a positive association between higher CD4 cell counts and cancer incidence." (PMID 28410587, 2017). "Moreover, the development of cancer vaccines, both therapeutic and preventive ones, have recently proven to be successful, so as to stimulate factors associated with improved survival rates in cancer patients, for example CD4+ T cells, CD8+ T cells and IFN- γ." (PMID 27483370, 2016). "Indeed, a decrease of CD4+ T cells has been associated with poor prognosis in advanced cancer." (PMID 27270307, 2016). "IL-10 is considered as another arm of inflammation associated cancer since both mice and humans deficient in IL-10 developed malignancy, IL-10 was required for the physiological protective, anti-inflammatory effects of CD4+ CD25+ regulatory lymphocytes to interrupt colon carcinogenesis in mice." (PMID 27886105, 2016).
cancer (continued). "Both human patients and experimental animals with advanced cancer often exhibit a poorly functioning immune system, manifested by decreased T cell proliferation, alteration in signal-transducing molecules, reduced CD4+:CD8+ ratios, and deficient production of Th-1 cytokines." (PMID 24053127, 2013). "Besides, the presence of CD4+CD25highFoxP3high T regulatory cells (Tregs) could be involved in the Vγ9Vδ2 cell deficiencies in cancer patients." (PMID 23717410, 2013). "Although not in the context of CD4-CTLs, similar cells have been described in CD4+ T cells in transplantation and cancer immunity in mouse models, thus establishing the potentially important role played by these stem-like cells in health and disease." (PMID 41499515, 2026). "Deconvolution of bulk RNA sequencing (RNA-seq) data reveals high content at baseline in cancer cells, immunosuppressive cancer-associated fibroblasts, FOXP3+ CD4+ regulatory T lymphocytes, and TREM2+ macrophages." (PMID 41519129, 2026). "Cytotoxic CD4+ T lymphocytes play pivotal roles across a broad spectrum of diseases, including cancer, infectious diseases, autoimmune disorders, and cardiovascular diseases." (PMID 41803090, 2026). "While cancer immunotherapies have primarily focused on activation of cytotoxic CD8 cells, CD4 T cell activity is also associated with survival and immunotherapeutic response in numerous cancers." (PMID 41542042, 2026). "Our DSP analysis further supports this idea by revealing that AR protein expression negatively correlates with CD45 abundance in ovarian and SARC cancers, and with CD4 in SARC, reinforcing AR’s role in promoting an immunosuppressive TME." (PMID 41486951, 2026). "IFN-γ-producing CD4+ T cells reactive to Akkermansia muciniphila, Bacteroides fragilis, and Enterococcus hirae correlate with favorable clinical outcomes in cancer patients." (PMID 41486167, 2026). "CD8+ T cells are critical cytotoxic components attacking and eliminating cancer cells, whereas CD4+ T cells sustain these cytotoxic responses and prevent exhaustion of CD8+ T cells." (PMID 41534468, 2026). "First, the highest incidence of cancers was observed in PWH with CD4 cell counts of less than 200/mm3." (PMID 40437996, 2025). "The heterogeneity of CD4+/CD8+ and NK cells is caused by different types of cancer, and the heterogeneity of NK cells is also caused by different stages of treatment." (PMID 40787472, 2025). "Previous studies have linked activated mast cells, activated CD4 memory T cells, and CD8+ T cells to poor prognosis across various cancer types." (PMID 40824962, 2025). "Cytokines such as IL-2 (promoting T-cell proliferation), IFN-γ (enhancing antigen presentation), and IL-10 (mediating immune suppression) critically regulate CD4+ T-cell function in cancer." (PMID 40860882, 2025). "For PWH, the median CD4+ T cell count was 440 cells/μL, 77% were on cART at the time of their cancer diagnosis, and 44% had an undetectable viral load (<400 copies/μL)." (PMID 40459946, 2025). "This limits glutamine entry into CD8+ T and CD4+ T cells, necessary for mitochondrion respiration under glucose deprivation, suppressing IFNγ expression and reducing cancer‐infiltrating T cell levels." (PMID 40547943, 2025). "The effective scores of CD8+ T cells, PD-1+CD8+ T cells, FOXP3+CD4+ T cells and FAP+ cells, which represents cancer-associated fibroblasts (CAFs), were higher in the DCB than those in the NDB." (PMID 40082418, 2025). "Protein expression analysis showed that im.CTCs express CD45 as well as other immune-related markers, such as CD3 and CD4, and the cancer stemness marker, CD44." (PMID 40707771, 2025). "Circulating lymphocytes, especially CD4+ T cells, play a vital role in immune defense against cancer cells." (PMID 39524006, 2025).